GDNF (glial cell derived neurotrophic factor)
Diseases named in the same sentence as GDNF in open-access papers (continued):
Sharing a sentence is not in itself a finding about the gene and the disease.
Parkinson disease (continued). "Due to these properties, neurturin (NRTN) and Glial cell-derived neurotrophic factor (GDNF), which belong to the GDNF family ligands (GFLs), have been assessed in clinical trials as a treatment for neurodegenerative diseases like Parkinson’s disease." (PMID 32252363, 2020). "In the Parkinson’s disease trial of GDNF, the visualisation provided immediate communication of harm signals, which had otherwise been contained within lengthy descriptive text and tables." (PMID 33353566, 2020). "In animal models of Parkinson’s disease, the injection of GDNF into the striatum recovers the nigrostriatal function by creating new synaptic connections." (PMID 33171879, 2020). "GDNF has shown mixed results in Parkinson’s patients to date which the study authors attribute to a potential insufficient GDNF exposure across the putamen." (PMID 33353566, 2020). "Laganiere and colleagues used a ZF-p65 fusion to upregulate the expression of endogenous GDNF in a 6-OHDA rat model of Parkinson’s disease." (PMID 33192264, 2020). "A range of studies have shown the efficient use of lentiviral vectors to overexpress genes of interest (e.g., heat shock protein-27) in stroke and glial cell line-derived neurotrophic factor (GDNF) overexpression in Parkinson’s Disease." (PMID 32183469, 2020). "GDNF has an imperative part in the case of degenerative diseases, such as Huntington's and Parkinson's, as it has been found that GDNF encourages survival of damaged midbrain dopaminergic neurons." (PMID 31824934, 2019). "The regenerative effects of GDNF in Parkinson’s disease have been questioned by studies using a rat model with overexpression of human wild-type α-synuclein." (PMID 30808022, 2019). "CR also improved behavioral and molecular signs in a MPTP-induced mouse model of Parkinson’s Disease (PD) by increasing the levels of the brain derived neurotrophic factor and the glial cell-derived neurotrophic factor." (PMID 31905682, 2019). "BDNF and GDNF were studied therapeutically in models of Parkinson disease (PD) and Huntington disease (HD), with loss of neurons that express TrkB and RET." (PMID 31244606, 2019). "Glial cell-line derived neurotrophic factor (GDNF) is a promising therapeutic agent to treat Parkinson’s disease (PD)." (PMID 30531868, 2019). "Glial cell-line derived neurotrophic factor (GDNF) is a promising therapeutic molecule to treat Parkinson’s disease." (PMID 30531868, 2019). "These works allowed Barry Hoffer and, later, Anders Björklund and their colleagues to initiate cell transplantation experiments as well as to use GDNF as the first NTF to restore dopamine neurons in animal models of Parkinson’s disease." (PMID 31105589, 2019). "PLGA microspheres have shown potential to overcome this crucial issue and cross the BBB to deliver anti-tumor drugs and glial derived neurotrophic factor (GDNF) for the treatment of neurodegenerative diseases such as Parkinson’s Disease." (PMID 30572957, 2018). "For this reason, GDNF is currently in clinical trials for the treatment of Parkinson’s disease (PD)." (PMID 30089897, 2018). "GDNF was purified and characterized as a survival factor of the embryonic dopaminergic neurons of the midbrain, which degenerate in Parkinson’s disease." (PMID 29617307, 2018). "Recombinant adeno-associated virus – Tet regulatory system has also been demonstrated in the rat to regulate the Glial cell line-derived neurotrophic factor (GDNF) gene expression for treating Parkinson’s disease." (PMID 30068696, 2018). "Although GDNF is a widely studied trophic factor, and its potential as a therapeutic agent for neurodegenerative diseases is well established including human clinical trials for Parkinson's disease, there are only few studies about the biology of β-GDNF." (PMID 29973907, 2018). "In previous clinical trials, GDNF treatment in Parkinson’s disease patients led to improved motor function and GDNF has been found to be down regulated in Parkinson’s disease patients." (PMID 29925387, 2018).
Parkinson disease (continued). "Glial cell line-derived neurotrophic factor (GDNF), a potential therapeutic factor for Parkinson’s disease (PD), exerts its biological effects through the Ret receptor tyrosine kinase." (PMID 28880247, 2017). "Intrastriatal transplantation of GDNF- (glial cell line-derived neurotrophic factor-) treated MSCs improved behavior in movement impairment in a rat model of Parkinson's disease." (PMID 28808446, 2017). "Glial cell line-derived neurotrophic factor (GDNF) is a potential therapy for Parkinson’s disease (PD) promoting survival and functional recovery of dopaminergic neurons when delivered to the degenerated striatum." (PMID 28493093, 2017). "GDNF signaling indisputably possesses potential therapeutic value for several pathologies, such as Parkinson’s disease or amyotrophic lateral sclerosis, among other diseases, where it has been tested using molecular and cellular approaches." (PMID 28878618, 2017). "Although administration of recombinant GDNF has proved highly effective in rodent models of Parkinson’s disease, a large clinical trial proved unsuccessful." (PMID 28468283, 2017). "The systemic administration of GDNF-expressing macrophages was found to significantly improve neuroinflammation and neurodegeneration in Parkinson's disease mice." (PMID 28912682, 2017). "A single AAV vector for tetracycline-regulated expression with rtTA (reverse tetracycline transactivator) has also been used for GDNF transgene expression in Parkinson’s disease models." (PMID 28208742, 2017). "For instance, MedGenesis Therapeutix and Pfizer made an agreement for joint development of methods for GDNF application and the convection enhanced delivery method in Parkinson’s disease." (PMID 27286696, 2016). "Based on these preclinical data, a RCT was conducted to examine the effect of NFs on Parkinsonism in human patients by delivering GDNF intracerebroventricularly." (PMID 27898033, 2016). "Protective effect of GDNF on dopaminergic neurons was demonstrated in several models of Parkinson’s disease." (PMID 27286696, 2016). "Glial cell line-derived neurotrophic factor (GDNF) is proposed as a therapeutic tool in Parkinson’s disease, addiction-related disorders, and neurodegenerative conditions affecting motor neurons (MNs)." (PMID 27445711, 2016). "GDNF has a potential therapeutic effect in different pathological paradigms, such as Parkinson's disease, brain ischemia, epilepsy and amyotrophic lateral sclerosis (ALS)." (PMID 25632161, 2015). "In a proteasome inhibitor lactacystin-induced model of Parkinson’s disease GDNF hypermorphic mice were protected from the reduction in striatal dopamine and failure of dopaminergic system function." (PMID 26681446, 2015). "Intracranial delivery of GDNF has been attempted for Parkinson’s disease (PD) treatment but with variable success." (PMID 26681446, 2015). "Because glial cell line-derived neurotrophic factor (GDNF) promotes survival of dopamine neurons in vitro and in vivo, intracranial delivery of GDNF has been attempted for Parkinson’s disease treatment but with variable success." (PMID 26681446, 2015). "Intracranial delivery of GDNF has been tested in clinical trials for treating Parkinson’s disease (PD); however, both the efficacy and the side effects of this treatment vary widely." (PMID 26681446, 2015). "Numerous studies on animal models of Parkinson’s disease (PD) have reported beneficial effects of GDNF on nigrostriatal DA neuron survival." (PMID 25762899, 2015). "Genetically-modified macrophages were utilized to deliver glial cell-derived neurotrophic factor for the treatment of Parkinson’s disease in a murine model." (PMID 25416164, 2014). "Recent work on neurotrophin levels in diseases of the brain have indicated that reduced neurotrophin levels (BNDF and glial derived neurotrophic factor – GDNF) correlate with the onset of neurodegenerative disorders such as Parkinson’s disease, AD, and HD." (PMID 24936207, 2014).
Parkinson disease (continued). "Many studies, carried out in a wide variety of rodent and primate models of Parkinson’s disease, have demonstrated the efficacy of GDNF, with clinical trials currently in progress." (PMID 24583850, 2014). "Glial cell line-derived neurotrophic factor (GDNF) is a neurotrophic factor for dopaminergic neurons with promising therapeutic potential in Parkinson's disease." (PMID 24324616, 2013). "Previous data have revealed that GDNF provides a potent neuroprotective role in animal models of Parkinson's disease, cerebral ischemia and motor neuron degeneration." (PMID 23151666, 2013). "GDNF is produced and released by astrocytes and it has a beneficial effect in experimental models of Parkinsonism." (PMID 24278772, 2013). "In clinical trials, GDNF has been used in the treatment of Parkinson's disease, BDNF in the treatment of ALS, and NGF as a therapeutic agent in Alzheimer's disease." (PMID 24391835, 2013). "In brain tissue of Parkinson's disease patients, GDNF, NGF, and brain-derived neurotrophic factor (BDNF) are deficient, hence the clinical trials of therapeutic GDNF injection into the brain of Parkinson's patients." (PMID 24023412, 2013). "Initial clinical studies involving Parkinson’s disease patients, for example, used a mechanical pump to infuse glial cell-derived neurotrophic factor (GNDF) into the lateral ventricles." (PMID 23284995, 2012). "Our findings are important because the results indicate that there is an endogenous process that can release endogenous BNDF and GDNF from reactive astrocytes upon onset of Parkinson's disease." (PMID 23251488, 2012). "The present results have demonstrated for the first time that astrocytes exhibit an endogenous self-repairing mechanism via release of BDNF and/or GDNF during very early stages of rat Parkinsonism of 6-OHDA-leisoned rats." (PMID 23251488, 2012). "In our forthcoming clinical trial of intraputaminal CED of GDNF for Parkinson's disease, we intend to use flow rates of up to 5 μl/min in order to limit the period of infusion to approximately two hours." (PMID 22264361, 2012). "Several trophic factors have been shown to promote the recovery or protect the dopaminergic system in animal models of Parkinson's disease, among which GDNF is thought to be the most efficacious." (PMID 21649894, 2011). "Neurotrophic factors, such as glial cell line-derived neurotrophic factor (GDNF), have shown great promise for protection and restoration of damaged or dying dopamine neurons in animal models and in some Parkinson's disease (PD) clinical trials." (PMID 20305789, 2010). "More importantly, the clinical use of GDNF for the treatment of the Parkinson's disease in humans is currently under evaluation." (PMID 19649251, 2009). "Cell lines overexpressing GDNF have neuroprotective effects in models of neurodegenerative disorders such as Parkinson disease and Huntington’s disease." (PMID 19461934, 2009). "In the last years a large number of studies demonstrated that GDNF provides potent neuroprotection in animal models of Parkinson's disease, motor neuron degeneration, cerebral ischemia, and limbic seizure." (PMID 19649251, 2009). "One study reports weight loss as a significant complication in a human clinical trial of ventricular injection of GDNF in patients with Parkinson disease." (PMID 19461934, 2009). "Brain-permeantmGlu2/3 receptor agonists are particularly promising for the experimental treatmentof Parkinson's disease for the ability to enhance striatal levels of GDNF(present data) and TGF-β." (PMID 19672295, 2009). "In relation to Parkinson's disease, clinical trials with recombinant GDNF protein were halted due to side effects, suggesting that more restricted expression of GDNF is desirable." (PMID 18402684, 2008). "Of note, GDNF is more effective than BDNF in protecting nigrostriatal neurons in the 6-OHDA rat model of Parkinson's disease." (PMID 18402684, 2008).
Parkinson disease (continued). "Similarly, in Rhesus monkeys with toxin-induced parkinsonism, GDNF administration significantly improved postural instability, rigidity, and bradykinesia, while also enhancing dopamine levels and increasing dopaminergic fiber density." (PMID 40595707, 2025). "For example, in Parkinson's disease models, restoring glial cell line-derived neurotrophic factor (GDNF) or similar factors has shown neuroprotective effects; however, protein delivery or gene therapy efforts for GDNF have struggled with distribution in the brain." (PMID 41438702, 2025). "Further markers of NMJ stability, notably brain-derived neurotrophic factor (BDNF), and glial cell line-derived neurotrophic factor (GDNF) have been assessed and a reduction in the levels of both have been associated with muscle loss and sarcopenia in Parkinson’s disease patients." (PMID 40772803, 2025). "GDNF was discovered as a secretion product from the rat B49 glioma cell line in 1993 and was suggested to be the innovative therapy for Parkinson’s symptoms since it protected the midbrain dopaminergic neurons from oxidative stress and other injuries and controlled microglial reactivity." (PMID 41562905, 2025). "Given its vital role in promoting the survival of dopaminergic neurons, GDNF has also demonstrated its ability to prevent neurotoxin-induced death of dopamine neurons and to facilitate functional recovery in various animal models of Parkinson’s disease." (PMID 40642294, 2025). "Previous studies from our group have shown that increasing GDNF in the mPFC significantly enhanced dendritic branching and the length and density of dendritic spines in Parkinson disease mice, thereby restoring the morphological structure and synaptic plasticity of pyramidal neurons." (PMID 39090173, 2024). "Genetic modulation of GDNF expression in these interneurons or the development of specific ligands are important focal points for future research to protect, support, and re-grow the dopamine neurons lost during the progression of Parkinson’s disease." (PMID 37410316, 2023). "Furthermore, it is well established that excess ectopically applied GDNF strongly stimulates striatal dopaminergic function when GDNF is delivered into Parkinson’s disease models, where striatal dopamine fibers degenerate." (PMID 37759827, 2023). "Therefore, based on the present study and our previous investigations we put forward a strategy of transplanting MSCs overexpressing GDNF to treat nervous system diseases such as stroke, Parkinson's, and Alzheimer's." (PMID 38008847, 2023). "Our findings demonstrate that neither an increase or loss of endogenous GDNF expression impacts dopamine neuron survival and recovery in proteasome inhibition model of Parkinson’s disease." (PMID 36690469, 2023). "Thus, viral delivery of glial cell line-derived neurotrophic factor (GDNF) clearly improved the survival and functional integration of transplanted human stem cells in a rodent model of Parkinson’s disease." (PMID 37580082, 2023). "GDNF sustains dopaminergic (DA) neurons and prevents their death in Parkinson’s disease (PD)." (PMID 36671553, 2023). "Since GDNF benefits the survival and regeneration of dopaminergic neurons, it has been exploited in a large number of clinical trials using infusion or gene delivery methods to treat Parkinson's disease." (PMID 36914965, 2023). "GDNF is currently recognized as a critical component of nigrostriatal neuron development, maintenance, and protection and as a possible factor in the maintenance and repair of dopaminergic neurons damaged by Parkinson's disease." (PMID 35360515, 2022). "Both BDNF and GDNF are known for its neuroprotective effects in different pathologies of central and peripheral nervous systems, including hypoxic and ischemic damage, traumas, neurodegenerative diseases, Parkinson disease, and Alzheimer disease." (PMID 36077134, 2022). "In another study, researchers studied GDNF gene therapy for the treatment of Parkinson’s disease." (PMID 36365243, 2022).
Parkinson disease (continued). "GDNF is an essential protein that is required to develop, maintain, and protect nigrostriatal neurons, particularly in protecting and restoring dopamine neurons affected by Parkinson's." (PMID 35360515, 2022). "Clinical trials for Parkinson’s disease confirmed the safety of GDNF intraparenchymal delivery." (PMID 36064599, 2022). "In summary, our experiments suggest that GDNF, which has been, and currently is, in clinical trials for Parkinson's disease, may bear potential to serve as a prospective means to improve nephron endowment in the future." (PMID 34032268, 2021). "The study results showed that GDNF therapy resulted in a 39% increase in OFF-medication motor abilities (according to the Unified Parkinson’s Disease Rating System, UPDRS), a 61% improvement in how participants viewed their capacity to perform everyday activities." (PMID 33716718, 2021). "Amgen (a biotechnology company) immediately began setting up clinical trials to determine whether the neuroprotective properties of GDNF would translate into humans, sensing that they were on to a potentially blockbuster cure for Parkinson’s." (PMID 33716718, 2021). "Furthermore, the neuroprotective effect of the human GDNF gene (hGDNF) was analyzed in a rotenone-induced chronic Parkinson’s disease model, using hGDNF-loaded NPs modified with Lf." (PMID 34371710, 2021). "Similarly, a 2010 study reported that macrophages that were engineered to deliver glial derived neurotrophic factor (GDNF) not only conferred neuronal protection, but also promoted axon regeneration in a mouse model for Parkinson’s disease." (PMID 32422973, 2020). "Additionally, initial trials of CED treatment for Parkinson’s disease using a glial cell-line-derived neurotrophic factor (GDNF) showed promising results." (PMID 32796527, 2020). "GDNF has been shown to have pronounced effects on the survival, growth, differentiation, and migration of various neuronal subpopulations, and its role in the treatment of human Parkinson’s disease is being evaluated through clinical trials." (PMID 32084217, 2020). "The first trials of GDNF for Parkinson’s disease were very promising." (PMID 32725425, 2020). "Huang and co-workers evaluated the delivery of human GDNF (hGDNF)-lactoferrin modified nanoparticles in a rotenone-induced chronic Parkinson’s model, concluding that the formulation can be used as a long-term therapy for the treatment of neurogenerative diseases." (PMID 33096803, 2020). "These properties make GDNF have potential in the treatment of Parkinson’s disease." (PMID 33336053, 2020). "Finally, in a 6-hydroxydopamine rat model of Parkinson’s disease, N4 improved the conditions of the animals more potently than GDNF." (PMID 32725425, 2020). "Based on the efficacy of GDNF as a survival factor of dopaminergic and motor neurons, establishing neurons expressing GDNF from iPS or ES cells could be beneficial for treating neurodegenerative diseases, such as Parkinson’s disease." (PMID 33150251, 2020). "Interestingly, weight loss was reported as a side effect of intraventricularly delivered high doses of GDNF in a clinical trial in Parkinson’s disease patients." (PMID 32911810, 2020). "Nasal delivery using GDNF encapsulated in a chitosan-coated nanostructured lipid carrier has been shown to improve behavioral as well as histological recovery in a rat model of Parkinson’s disease." (PMID 32725425, 2020). "Likewise, injection of autologous BM-MSCs expressing glial derived neurotrophic factor (GDNF) into the lateral ventricle of several patients with Parkinson disease led to beneficial results." (PMID 31795466, 2019). "Healthy rats given the combinational treatment, with the implant being applied to target the striatum (BDNF) and sustantia nigra (GDNF) with the hope of assisting transplant survival and long-term axon extension, respectively, in future work with animal models of Parkinson’s disease." (PMID 31427916, 2019).